JAG1 (jagged canonical Notch ligand 1)
Diseases named in the same sentence as JAG1 in open-access papers (continued):
Sharing a sentence is not in itself a finding about the gene and the disease.
cancer (continued). "Additionally, the current study revealed other DEGs previously linked with cancer, such as the downregulated genes LIM zinc finger domain containing 2 (LIMS2; also known as PINCH2) and jagged canonical Notch ligand 1 (JAG1)." (PMID 40137900, 2025). "Overall, these studies highlight the critical roles of IL6 and IL6R, as well as CD46 and JAG1, in the survival and invasive capacity of cancer cells, and their broad promise as targets for antitumor therapies, as well as exploring the possibility of combining them with other therapeutic agents." (PMID 38571938, 2024). "As JAG1 is associated with tumorigenesis and aggressiveness in various tumors, targeting JAG1 may be a suitable strategy for anti-cancer therapy." (PMID 38092725, 2023). "Moreover, Jag1 overexpression in cancer cells can activate Notch signaling in adjacent endothelial cells." (PMID 36925919, 2023). "Additionally, it has been reported that JAG1 overexpression is present in many types of cancer and correlates with a poor clinical prognosis." (PMID 37781534, 2023). "JAG1 is highly expressed in various cancer types and correlates with cancer invasiveness." (PMID 38092725, 2023). "Due to the relevant role of JAG1 expression in various aggressive cancers, in this study, we aimed to identify novel specific anti-JAG1 scFvs with the potential for the development of therapeutic products, being either in the antibody format or in a cell modality setting." (PMID 36979394, 2023). "The further characterization of these CARs revealed that engineered primary CAR-T cells expressing the J1.B5 Ab scFv in a third-generation design became activated only in the presence of JAG1-expressing cells and effectively and specifically killed JAG1-positive cancer cells." (PMID 36979394, 2023). "Similarly, we investigated the correlation of protein levels between JICD1-binding proteins and JAG1 in proteomics datasets from Cancer Cell Line Encyclopedia (CCLE)." (PMID 37834227, 2023). "Given their specificities and nanomolar affinities and considering the oncogenic role of JAG1 as well the great potential of cell therapies against cancer, six anti-JAG1 CARs containing the scFvs from J1.B5 or J1.F1 Abs were generated featuring second- or third-generation designs." (PMID 36979394, 2023). "Moreover, neutralizing JAG1 inhibited cancer cell plasticity, which otherwise produced drug resistance by maintaining cancer heterogeneity." (PMID 35673567, 2022). "Additionally, we experimentally demonstrated that neutralizing JAG1 inhibited cancer cell plasticity." (PMID 35673567, 2022). "Enriched pathways for upregulated miRNAs included: “Chemical carcinogenesis–receptor activation” (p-value = 0.018) associated with ESR1, FGF18, JAG1, KPNA6, PPARA genes; the pathway “Proteoglycans in cancer” (p-value = 0.089) associated with genes ESR1, FRS2, HIF1A, PDCD4." (PMID 36359024, 2022). "JAG1 overexpression has been detected in various cancers and is related to poor clinical prognosis." (PMID 35349480, 2022). "However, the role of JAG1 expressed in PDAC organoids for cancer cell plasticity remains poorly understood." (PMID 35673567, 2022). "JAG1 plays a carcinogenic role in many types of malignant tumors." (PMID 36539520, 2022). "We detected JAG1 protein in 200 BC tissues and 47 para-cancer breast tissues by IHC." (PMID 36539520, 2022). "Due to elevated JAG1 in ICC/IDC cancer cells, NOTCH signaling may be increased in cells directly adjacent to ICC/IDC." (PMID 36229464, 2022). "As another candidate inhibitor of the NOTCH pathway, we suggest that combining conventional therapy with JAG1 neutralization to inhibit CICs and cancer cell plasticity might offer a synergic effect." (PMID 35673567, 2022). "JAG1 expression in BC tissues was higher than that in para-carcinoma tissues." (PMID 36539520, 2022).
cancer (continued). "Additionally, association analysis of CMTM6 mRNA levels with Wnt target genes (TCF4, LEF1, CD-44, MMP14, ENC1, ID2, PPARA, and JAG1) from the cancer genome atlas HNSCC cohort using GEPIA showed a positive correlation (r > 0.2)." (PMID 33434185, 2021). "Elevated expression of JAG1 correlates with poor prognosis in many cancer type." (PMID 33430387, 2021). "Additionally, the expression of Jag1 in ECs can activate the Notch signal of progenitor cells and induce pericyte differentiation or further modulate the properties of cancer stem cells." (PMID 33850225, 2021). "The similar mechanisms upstream of JAG1 have been exhibited by studies focusing on other cancers." (PMID 33292218, 2020). "Activating the Notch1 signaling pathway is necessary to maintain cancer stem cells, and demands attachment of its ligands Jagged 1 (JAG1), JAG 2, and δ-like, accompanied by the proteolytic releases of the Notch intra-cellular domain (NICD), and activating NICD down-stream target genes." (PMID 32280305, 2020). "Jagged1 (JAG1) has been reported to play a role in multiple types of cancer." (PMID 32377169, 2020). "Silencing of DANCR could restore sensitivity to docetaxel treatment in vitro through the proposed DANCR/miR-34-5p/JAG1 axis, resulting in lower expression of P-glycoprotein and MRP1 and LRP1 proteins, which are associated with drug resistance in cancer." (PMID 32756406, 2020). "This demonstrates that JAG1 is important in sustaining the survival of cancer cells." (PMID 30231940, 2018). "Similarly, Jag1 secreted from tumor endothelial cells promotes the cancer stem cell phenotype of colorectal carcinoma cells." (PMID 29996493, 2018). "Additionally, both gal-3 and JAG1 are overexpressed in several malignancies and are largely appreciated as potential targets for cancer therapy, including antiangiogenic therapy." (PMID 28533486, 2017). "To verify whether JAG1 plays a critical role in regulating cancer metastasis, we used overexpression and RNAi silencing approaches to modulate JAG1 transcriptional expression and performed transwell migration and invasion assays." (PMID 26930648, 2016). "The expression of NOTCH-3 and JAG-1 is highly correlated and found to be upregulated in cancer." (PMID 26762567, 2016). "We found a strong positive correction (P<0.0001) between KDM2A and JAG1 in these cancer patients." (PMID 27029061, 2016). "Importantly, JAG1 expression can be induced by other signaling pathways that are important in cancer such as TGF-β, WNT/β-catenin, IL-6, and NF-κB, as well as by the Notch pathway itself." (PMID 25309874, 2014). "JAG1 acts as a key ligand of the Notch1 receptor in cancer development." (PMID 24659709, 2014). "JAG1 has a number of advantages as a target for anti-cancer therapy over other Notch ligands." (PMID 25309874, 2014). "We found that the Notch signalling in the cancer cells was strongly activated when cells were co-cultured with rat astrocytes and this activation was almost completely abolished by the knockdown of JAG1 expression in astrocytes and the treatment of the cells with γ-secretase inhibitor, DAPT." (PMID 23495140, 2013). "Furthermore, bioinformatic analysis of miR‐34a targets in various cancers identifies numerous target genes such as Jagged 1 (JAG1), CD44, SRY (sex determining region Y)‐box 4 (SOX4), Notch homolog 2 (NOTCH2), Matrix metallopeptidase 9 (MMP9), Interleukin 6 (IL‐6), and SMAD family member 4 (SMAD4)." (PMID 40336533, 2025). "Consequently, the reduced expression of JAG1 may potentially suppress JAG1/Notch signaling activity and exhibit an anti-cancer effect." (PMID 40137900, 2025). "There is rising evidence that cancer cells and fibroblasts interact directly through the cell surface ligand JAG1 and NOTCH receptors, and this, in turn, may also lead to fibroblast transformation into CAFs, driving the process of CAF‐mediated angiogenesis and extracellular matrix modification." (PMID 39245631, 2025).
cancer (continued). "Consequently, the results of our study elucidate the fact that the BAP31-induced upregulation of GAL-3 expression in cancer cells, along with its subsequent secretion into the conditioned media, is sufficient to initiate JAG1—regulated endothelial cell morphogenesis towards angiogenic phenotypes." (PMID 38474195, 2024). "In addition, JAG1 profoundly affects cancer cell invasion and metastasis." (PMID 38092725, 2023). "In addition, in supratentorial (ST) EPN, NOTCH1 expression was associated with cancer stem cell (CSC) markers, VEGFA and L1CAM, and the ST_EPN_RELA subtype showed the activation of selected key members of the Notch signaling pathway (NOTCH1, JAG1, JAG2, HES4)." (PMID 36293188, 2022). "Furthermore, stimulating ECs with JAG1 expressed on cancer cells could increase the expansion and differentiation of T-reg by up-regulating TGFB1." (PMID 35673567, 2022). "Jagged-1 (JAG1), a cell surface protein which is one of five canonical ligands of Notch receptors, triggers Notch signaling through cell–cell interaction and is associated with cancer angiogenesis, proliferation, and the epithelial-mesenchymal transition (EMT) signaling pathway." (PMID 35054034, 2022). "Therefore, we hypothesized that NOTCH pathway activation in ECs by JAG1 on cancer cells would induce WNT5B expression." (PMID 35673567, 2022). "However, the molecular mechanism by which JAG1 is activated in cancer cells is largely unclear." (PMID 27029061, 2016). "Previous studies have proposed that the aberrant activation of the JAG1-Notch1 signaling pathway may protect cancer cells from cisplatin-induced cell apoptosis and that the signaling activity is inversely correlated with the cisplatin sensitivity of human cancers." (PMID 24659709, 2014). "In this study, the link between increased levels of PRL observed during pregnancy, overactivation of the PRL/STAT3/JAG1 pathway in CRC, and increased EMT and cancer cell stemness was established by in vitro and in silico experimentation." (PMID 41501898, 2026). "In vitro data was then used to link pregnancy levels of PRL to increased JAK2/STAT3 and JAG1/NOTCH1 signaling resulting in increased epithelial-to-mesenchymal transition (EMT) and cancer cell stem-like protein expression." (PMID 41501898, 2026). "For the first time, we demonstrate that pregnancy-level PRL directly enhances JAK2/STAT3 and JAG1/NOTCH1 signaling in CRC cells, promoting epithelial-mesenchymal transition (EMT) and cancer stem-like protein expression." (PMID 41501898, 2026). "Both expression and DEG enrichment of JAG1, DLL1, and NOTCH4 significantly increased after anti-cancer therapy in BIC." (PMID 39074091, 2024). "In HNSC, both expression and DEG enrichment of JAG1, DLL1, and NOTCH2 significantly increased after anti-cancer therapy, while DLL3 and NOTCH4 significantly decreased." (PMID 39074091, 2024). "Our results demonstrated that Jag1/2 KO led to the early onset of foregut SCC, characterized by severe epithelial dysplasia and highly proliferative cancer cells." (PMID 38750026, 2024). "In addition, about 30% of HNSCC or skin cancer cases show overexpression of JAG1 or JAG2, which may be in line with the activation of the Notch pathway at least in some cases, especially aggressive, late-stage cancers, and is associated with poor patient outcome." (PMID 37760535, 2023). "Mutations in Notch ligands are found more rarely in the same cancers, ranging only between 0.5 and 3% for DLL1, DLL3, DLL4, JAG1, or JAG2." (PMID 37760535, 2023). "PTTG3P, detected in various cancer types such as colorectal, tongue, and prostate cancer, shares high homology with the 3′ UTR of JAG1, an oncogenic protein that activates the NOTCH pathway." (PMID 37627052, 2023). "The newly released growth factors go on to close the vicious feedback loop between the cancer cells and their newly created niche, as one of the TGF-β targets is JAG1." (PMID 36605720, 2022).
cancer (continued). "Collectively, these findings support that ICC/IDC cancer cells have high inter-patient heterogeneity, but commonly upregulate SCHLAP1 and TNFα signaling via NFĸB pathway member JAG1." (PMID 36229464, 2022). "We found that plasticity, which re-programmed CD44(-) differentiated cancer into CD24(+)CD44(+)EpCAM(+) CICs, was inhibited when JAG1 was neutralized." (PMID 35673567, 2022). "In tumorigenesis and cancer progression, JAG1 is involved in CSC functions, immune regulation, cancer proliferation, angiogenesis, epithelial-to-mesenchymal transition (EMT), and metastasis." (PMID 35249111, 2022). "Accordingly, cancer cells cultured on 2D laminin/collagen exhibited a higher expression of TRB3 and JAG1, when compared to dish cultured groups." (PMID 35585515, 2022). "As there are many Notch ligands—Jag1, Jag2, DLL1, DLL3, and DLL454—we wanted to identify which Notch ligand(s) is/are involved in stemness induction in cancer cells." (PMID 34911937, 2021). "Jagged1 (JAG1), as a member of oncogenes, activated the Notch signal pathway related to tumorigenesis for some types of cancers." (PMID 32195180, 2020). "The BD has been demonstrated to exhibit anti-proliferative and pro-apoptotic effects against various cancer cell lines via inhibition of the key regulatory signaling pathways like PI3K/AKT/mTOR, JAK/STAT, JAG1/Notch." (PMID 36046775, 2020). "JAG1, one of the ligands of NOTCH, has a proven role in cancer progression and in particular in EMT." (PMID 30979003, 2019). "GLI3, SMURF1, RBPJL, JAG1, LFNG and DTX2 were some of the most amplified genes present in at least 18 cancers." (PMID 31523055, 2019). "In mouse embryonic fibroblast (MEF) and a variety of human cancer cell lines, PI3K has been shown to induce Jag1 expression via the Mammalian Target Of Rapamycin Kinase (mTOR) pathway to positively regulate Notch signaling." (PMID 30716082, 2019). "During the process of dedifferentiation, multiple genes that were demonstrated to be pivotal in cancer stem cell properties were induced, including PDGFRB, NOTCH1, JAG1, HES1, and HEY1 of the Notch signaling, SNAI1 and SNAI217–20." (PMID 29991717, 2018). "The top-scoring genes recurring in the four gene sets included key cancer genes, KAT2A, SKP1, FZD1, JAG1 and PSEN2." (PMID 28473661, 2017). "TNF-α can also induce the expression of many oncoproteins through NF-κB or p38 signaling, such as JAG1, Fascin, VEGF and MMP2/MMP9, to promote the development of cancers." (PMID 28938560, 2017). "Transcript levels of ALK2, the NOTCH ligand JAG1, and NOTCH1 were significantly higher in the malignant tumor group compared to the benign group." (PMID 29259971, 2017). "Reports indicate that NOTCH-3, JAG-1, and DLL-4 are among the most altered notch signaling genes in cancer." (PMID 26762567, 2016). "In contrast, transcripts encoding several canonical Notch signalling components, including DLL1, JAG1, NOTCH1 and HES2, were down-regulated in cancer cells." (PMID 25864518, 2015). "B-ALL stroma express JAG1, JAG2, and DLL1, and these ligands are responsible for the synergistic activation of cancer cells that expressed Notch3 and Notch4, which ultimately support B-ALL cell survival." (PMID 25309874, 2014). "Furthermore, miR-34a downregulates Notch, Jag1, and SIRT1, impairing cancer stem cell self-renewal and reducing cancer cell invasiveness 70-75." (PMID 39512697, 2024). "Studies in primary T cells demonstrated that one CAR harboring the J1.B5 scFv significantly induced effective T-cell activation in the presence of JAG1-positive, but not in JAG1-knockout, cancer cells, and enabled specific killing of JAG1-positive cells." (PMID 36979394, 2023). "In contrast, Jag1 was detected in desmin-positive HSCs present in area #2, but not in cancer cells in both areas." (PMID 35064244, 2022). "To determine whether cancer plasticity was affected by the NOTCH/JAG1 pathway, we cultured the organoid-derived differentiated CD44(-) cancer cells with ECs after neutralizing JAG1." (PMID 35673567, 2022).
cancer (continued). "Therefore, Jag1-ICD exerts a cytoprotective effect on Jagged1 CRC cells, promoting tumoral cells to escape from cancer drugs and sustaining the chemoresistance." (PMID 35847908, 2022). "Both JAG1 and NOTCH1 silencing decreased in vitro cancer spheroid formation." (PMID 35249111, 2022). "In this study, we found that the JAG1 level on PDAC organoids was increased by ductal differentiation, and JAG1 consequently increased the WNT5B and TGFb1 levels by stimulating ECs, leading to cancer cell plasticity and anti-inflammatory microenvironment." (PMID 35673567, 2022). "This further supports the view that Notch3 induces endothelial cell death independently of Notch canonical signalling pathway, and that the expression of Jag-1 by cancer cells can cell non-autonomously rescue endothelial cell death." (PMID 28719575, 2017). "Given that APL13 can stimulate JAG1/Notch3 signaling in ischemic hearts, in this study we investigated whether the treatment with APL13 activates JAG1/Notch3 to promote cancer proliferation in CRC." (PMID 29254197, 2017). "Present data show that NILCO molecules (Notch1, Notch2, Notch3, Notch4, DLL4, and JAG1) and targets (Survivin, Hey2, IL-1R tI, and OB-R) were expressed in EmCa regardless of ethnicity and cancer type." (PMID 28659656, 2017). "Not surprisingly, Jag1 is enriched in aggressive cancers such as basal‐like breast cancer (BLBC) and can contribute to the abnormal vasculature typically observed in cancers." (PMID 28548345, 2017). "Although a specific role for JAG1 was not investigated, these cells do have higher JAG1 expression than typical luminal-like cancers." (PMID 25309874, 2014). "Among the ligands, DELTA1 (DLL1) expression was strongly and significantly decreased in cancer tissues, whereas JAGGED1 (JAG1) and JAGGED2 (JAG2) mRNA levels were not significantly changed." (PMID 25167871, 2014). "Furthermore, we identified several significantly upregulated genes (CD46, JAG1, IL6, and IL6R) that may positively correlate with cancer cells' survival and invasive capabilities in this subtype." (PMID 38571938, 2024). "All the studies indicated a negative correlation between JAG1 and cancer prognosis." (PMID 36923423, 2023). "Therefore, JAG1 signaling and/or its active intracellular domain, JICD, can be considered an alternative therapeutic target for advanced PCs and detection marker of PCSC bulks from patients who experience therapeutic failure or have resistant and recurrent cancer." (PMID 36428807, 2022). "It was revealed that apelin could promote cancer cell proliferation by increasing expression of factors involved in cell proliferation including cyclin D1, Ki-67, proliferating cell nuclear antigen (PCNA), and activating pathways like JAG1/Notch3, ERK1/2, and PI3K/Akt." (PMID 33912466, 2021). "The CTGF, IGFBP2, JAG1, and SPARC promoters can provide higher transgene expression in fibroblasts than in cancer cells, but the nonspecific viral promoters CMV, SV40, and the recently studied universal PCNA promoter have the same features." (PMID 33804861, 2021). "Genes coding for proteins supporting cancer cells survival or proliferation such as FOXD1 or EIF5A appeared up-regulated in resistant and not in sensitive, while E-cadherin, CLDN7, MDK, PKDCC, and JAG1 were more down-regulated." (PMID 27835869, 2016).